KRAS (KRas proto-oncogene, GTPase)
Diseases named in the same sentence as KRAS in open-access papers (continued):
Sharing a sentence is not in itself a finding about the gene and the disease.
tumor (continued). "In conclusion, BAY-293 exhibits synergy with drugs in dependence of the tumor type and specific KRAS mutation." (PMID 36048281, 2022). "It has been claimed that KRAS mutations promote T cell infiltration and enhance tumor immunogenicity, thereby improving the immune efficacy of PD-1/PD-L1 inhibitors." (PMID 35979370, 2022). "Serum KRAS mutations, especially the KRAS G12D mutation, in preoperative cell-free circulating tumor DNA are associated with the poor prognosis of resected PDAC patients." (PMID 35275973, 2022). "Considering the low VAFs of the pathogenic variants of the three driver genes in the first recurrent tumor, droplet digital PCR (ddPCR) of the identified KRAS variant was performed." (PMID 35255903, 2022). "Mutations in CTNNB1 (B) and KRAS (K) were assigned to tumor samples with a non-synonymous mutation and/or CNV gain for a given gene." (PMID 36457077, 2022). "Mutations in oncogenes, such as KRAS; and subsets of loss-of-function mutations in tumor suppressors, such as FBXW7 or STK11, can cause resistance to DNA damage based therapies." (PMID 35477555, 2022). "Prevalence of KRAS mutation varied widely across tumor systems, ranging from 0% in patients with endocrine system tumors to 50.0% in patients in urinary system disease." (PMID 35359599, 2022). "MET PET parameters showed significant associations with tumor location, sex, symptoms, KRAS variant, and HCG." (PMID 35130327, 2022). "As with the CodeBreaK100 trial, inclusion for KRYSTAL-1 was limited to tumours harbouring a KRAS G12C mutation." (PMID 36284306, 2022). "Nevertheless, romidepsin induced tumor growth inhibition in our mouse model, confirming the activity of romidepsin in a KRAS-mutated tumor model in which glucose is presumably preferred over glutamine." (PMID 35681624, 2022). "The efficacy of all combinations is critically dependent on tumor type and on specific KRAS mutations." (PMID 36048281, 2022). "Comparison between mutated and wild type KRAS tumors revealed a trend toward right-sided tumours (30% and 4.3% vs 16% and 1.1%, p-value = 0.032, respectively) and peritoneal metastases (34% vs 19%, p-value = 0.014)." (PMID 35505757, 2022). "KRAS mutation causes aberrant activation, which is associated spontaneous tumor development in KRAS-driven cancer." (PMID 36741696, 2022). "Several studies have identified many tumor suppressor miRNAs targeting the KRAS oncogene in human cancers, which affect cancer-associated cellular and molecular mechanisms." (PMID 34489556, 2022). "In 1984, an activating KRAS G12R point mutation was first identified in the tumour tissue of a 66-year-old man with squamous cell lung carcinoma, which was not present in normal parenchymal or lymphocytes." (PMID 36284306, 2022). "These revealed that in patients with LUAD (a tumor with high KRAS mutation frequency), high KRAS/CCL2/IL1B expression levels portended 93% increased odds of death regardless of smoking status (upper left)." (PMID 35327394, 2022). "A known pathogenic KRAS mutation (Gly12Asp) was found in seven tumor samples and one dysplasia sample of four patients." (PMID 35897137, 2022).
tumor (continued). "Previous studies have shown that tumor KRAS gene expression levels are influenced by the KRAS mutational status and KRAS mutation leads to an increase in KRAS mRNA level, which can enhance the downstream signaling pathways." (PMID 35785187, 2022). "In this analysis of a large cohort of NSCLC patients with KRAS mutant tumours, we observed co-occurring KRAS mutations in 8% of the KRAS c.34G>T mutant NSCLC tumours, of which KRAS c.35G>T was most frequently detected." (PMID 35177674, 2022). "Cdk4 gene ablation was associated with tumour death in genetically engineered KRAS-mutant NSCLC mouse models providing the preclinical rationale for CDK4 inhibition in NSCLC." (PMID 36284306, 2022). "KRAS mutations regulate the tumour microenvironment and alter tumour stroma, immune cell infiltration and cytokine expression." (PMID 36284306, 2022). "Considering the tumor-suppressive effect of miR-181a via downregulation of KRAS and the role of the KRAS mutation in vascular malformations, it is assumed that H19 has an indirect effect on KRAS upregulation." (PMID 34489556, 2022). "The genomic analysis of KRAS mutations revealed that tumor tissues prepared by LMD technique significantly enriched neoplastic cellularity, especially from bulk tumors with low neoplastic cellularity." (PMID 36266629, 2022). "The findings led to the conclusion that genetic subtyping of primary tumors for KRAS mutation or cMET amplification would be valuable for predicting tumor response to the pathway inhibition." (PMID 36686779, 2022). "Most PDAC is caused by sporadic somatic mutation and the sequencing of tumor samples has demonstrated that the majority of these tumors (over 90%) contain activating mutations in the KRAS proto-oncogene." (PMID 35408514, 2022). "Tumor organoids harboring KRAS, NRAS, BRAF, or PIK3CA hotspot mutations exhibited a relatively higher IC50 and area under the drug response curve (AUC) for cetuximab than organoids without hotspot mutations in these genes." (PMID 34850547, 2022). "A recent study found that the activation of Wnt/β-catenin alone does not promote tumor development but concomitant activation of Wnt/β-catenin signaling and KRAS mutation (G12D) led to an increase in tumor number and size." (PMID 35887120, 2022). "In our study, the KRAS expression levels in various tumor cells were associated with prognosis and immune cell infiltration." (PMID 36330448, 2022). "Of note, 83% (5/6) of the ypT0 NAT sub-group displayed KRAS mutations, although the primary tumours were supposedly cleared." (PMID 35194118, 2022). "The different patient characteristics suggested that the CRC was similar in male and female patients in terms of age group (age ≤ 40 years, vs. >40 years), location of the tumor, pathological staging, grade, KRAS mutation status and BRAF mutation status." (PMID 35565379, 2022). "In this regard, many tumor suppressor miRNAs have inhibitory effects on KRAS-associated tumrigenesis by downregulating KRAS expression." (PMID 34489556, 2022). "KRAS mutation was only related to the depth of tumor invasion whereas KRAS multi-site mutations were related to mucus components and tumor size." (PMID 35837115, 2022). "It should also be noted that KRAS mutational status was resolved either through analysis of the metastasis or of the primary tumour, depending on specimen accessibility." (PMID 35326950, 2022).
tumor (continued). "Different co-occurring mutations with KRAS exhibit unique tumor behaviors and have different gene expression profiles." (PMID 35573694, 2022). "The meta-analysis of interaction terms showed that there was a significant interaction between tumor side and KRAS mutational status." (PMID 35159066, 2022). "A mismatch between KRAS G12C mutation allelic ratio and tumor cellularity was found in 24.3% of the analyzed samples." (PMID 35205778, 2022). "In vivo, while the control cancer cells induced tumor formation in nude mice, silencing of Furin (KO) reduced the ability of cells with KRAS or BRAF mutation to induce tumor growth." (PMID 35267511, 2022). "The presence of oncogenic KRAS mutation was also reported to be involved in the activation of CAFs and to regulate tumor cell signaling via stromal cells." (PMID 36076911, 2022). "Consistently, at the risk factors analysis for OS, a KRAS mutated tumor, an N2 CRC, a larger size of the liver metastases, and elevated preoperative CEA were found to be independently associated with worse survival." (PMID 36010944, 2022). "KRAS mutations have been shown to extend their oncogenic effects beyond the cancer cell, influencing the tumor microenvironment." (PMID 36010567, 2022). "Here we investigated if additional KRAS mutations co-occur with KRAS G12C (c.34G>T) in NSCLC tumours and if such mutation co-occurrence affects cellular response to G12C-specific inhibitors." (PMID 35177674, 2022). "It is clear that PDAC, as a tumor that also contains a high percentage of KRAS mutations, is likely to benefit from this." (PMID 36291766, 2022). "The possible mechanism of the superior response to ICIs is that KRAS mutation is related to tumor immunogenicity and the inflammatory tumor microenvironment." (PMID 36508072, 2022). "In a recent study, autophagy-dependent ferroptosis via the release of oncogenic KRAS protein drove tumor-associated macrophage polarization." (PMID 36547083, 2022). "Increasing use of mutational analysis techniques in an effort to improve understanding of tumor biology and identify potential therapeutic targets has led to the identification of recurrent KRAS mutations in MLAs." (PMID 35865471, 2022). "As a predictive marker, KRAS has been linked to round shape, nodules in non‐tumour lobes, multiple small nodules, as well as, general radiomic profiles." (PMID 35965430, 2022). "On the other hand, patients with KRAS wild-type tumor have a longer survival rate compared to the KRAS mutation patients, regardless of the POLQ expression level." (PMID 36077614, 2022). "N stage, well-differentiated tumour, surgical margin, and KRAS-G12D mutation were independent prognostic factors for DFS." (PMID 36582783, 2022). "Tumor MET parameters also had significant differences according to tumor locations, sex, symptoms, and KRAS mutation." (PMID 35130327, 2022). "Clinical responses to MEK-inhibitor-based therapy regimens have been observed in patients with KRAS mutation in certain tumor types." (PMID 36551764, 2022). "For KRAS-G12C vs. other KRAS mutations, the primary tumor sites were the right colon in 28% vs. 34%, the left colon in 35% vs. 30%, and the rectum in 37% vs. 36%." (PMID 35251991, 2022). "Taken together, these findings further validated the occurrence of glucose metabolic reprogramming in CCA and identified the presence of KRAS mutations as candidate drivers for the activation of the serine-glycine pathway in this type of tumour." (PMID 35619118, 2022).
tumor (continued). "Overall, 2495 NSCLC patients (independent from tumor stage) were tested for KRAS mutations between January 2017 and October 2021." (PMID 35887862, 2022). "As a predictive marker, KRAS has been linked to a round shape, nodules in non-tumour lobes, and multiple small nodules, as well as general radiomic profiles." (PMID 35406429, 2022). "Multivariate analysis indicated that tumor site and KRAS mutation were independent prognostic CRC patients (P<0.05)." (PMID 35463728, 2022). "The disease control rate was similar in patients with BRAF mutation and BRAFwt/KRASwt, but lower for patients with KRAS mutated tumours." (PMID 35574322, 2022). "Activating KRAS mutations results in the accumulation of active GTP-bound RAS able to activate several downstream signaling pathways with tumor cell proliferation." (PMID 35267628, 2022). "Despite the intricacy of PDAC initiation, it has been well established that the KRAS mutation is a key driver of tumor progression." (PMID 35684434, 2022). "Combining the genetic mutational profile (i.e., KRAS in specific cases) with tumour characteristics helps patient selection and achieves the best prognosis after CRLM resection." (PMID 35326950, 2022). "In a sub analysis of CGP of liquid biopsies, we observed a similar frequency and distribution of KRAS alteration and mutation isoforms pan-tumor." (PMID 36494601, 2022). "Multivariate Cox regression model analysis showed that N stage, surgical margin, tumour differentiation, and KRAS-G12D mutation were independent prognostic factors for DFS and OS." (PMID 36582783, 2022). "SOS1 depletion or specific genetic inactivation of its GEF function has been shown to reduce the survival of KRAS-mutated tumor cells." (PMID 35406400, 2022). "Apart from genetic alterations associated with spontaneous tumor development, it has been increasingly appreciated that KRAS mutation also exhibits a broad impact on the tumor microenvironment, which helps to promote and maintain the malignancy of cancer." (PMID 35359599, 2022). "Another type of mutation, KRAS mutations, are correlated with an inflammatory tumor microenvironment and tumor immunogenicity, resulting in good response to ICIs in advanced patients." (PMID 35255999, 2022). "In a KRAS mutated carcinoma model, autophagy deficiency-induced mitochondrial hyperfission attenuated the invasion of tumor cells." (PMID 35463323, 2022). "Of note, patients with KRAS/NRAS mutated tumours had numerically superior survival if allocated to the control arm." (PMID 35574322, 2022). "The tumor was positive for Kirsten rat sarcoma virus oncogene KRAS-G12C mutation and had high programmed death-1 ligand expression." (PMID 36329437, 2022). "Each set included separate meta-analyses for KRAS-mutated and wild-type patients as well as for the interaction between tumor site and KRAS status." (PMID 35159066, 2022). "Specifically, patients who had detectable KRAS mutations from plasma cfTNA that was concordant with tumor tissue had significantly shorter RFS (p < 0.0001) than those who were ctDNA negative." (PMID 36232820, 2022). "Since the presence of RNF43 and KRAS mutations in IPMNs predicts future development of advanced neoplasia from PCLs, patients with these genetic anomalies warrant surveillance, surgery, and/or targeted therapeutics such as Wnt/β‐catenin inhibitors." (PMID 35229994, 2022). "Across tumor types, KRAS G13D and G12D were associated with the highest levels of MSI high relative to other KRASm isoforms." (PMID 36494601, 2022).
tumor (continued). "In patients with KRAS mutations, one was unresectable, and one tumor achieved complete pathological response." (PMID 35681755, 2022). "To further evaluate the enrichment for neoplastic cells, we analyzed KRAS mutations in the tumor samples." (PMID 36266629, 2022). "The activation of CXCL2 and its associated receptor CXCR2 by KRAS signaling is thought to suppress immune response and promote tumor proliferation." (PMID 36033462, 2022). "All KRAS mutations, namely G12D, G12S, G12V, and Q61H, were confirmed to be truncal events as they were present in all sectors of the tumors, underscoring KRAS mutations’ role as an early driver of tumor initiation." (PMID 34290355, 2022). "The findings also showed that the use of CRISPR/Cas9 to target K-Ras in mice with KRAS-mutated CRC significantly reduced tumor size and enhanced the effect of cetuximab in the induction of apoptosis." (PMID 35715750, 2022). "The first was inflammation-related pathways, such as the IL6/JAK/STAT3 signalling, inflammatory response, IL2/STAT5 signalling, TNF-alpha signalling via NFKB, and KRAS signalling pathways, which have been proven to be associated with tumours." (PMID 35246158, 2022). "The association of NK cell dysfunction with tumor progression was revealed in KRAS-driven lung cancer, in which NK cells protect tumors at the early stage but cannot prevent tumor progression." (PMID 36241658, 2022). "Tumor tissue biopsy testing is the standard of care to assess RAS (KRAS/NRAS) mutation in these patients." (PMID 36551560, 2022). "Because most human PDACs carry mutations in KRAS, p62 accumulation and activation of downstream tumor-promoting signaling also likely play an important role in the pathogenesis and progression of human PDAC." (PMID 35354432, 2022). "At a genomic level, initial activating mutation in KRAS is the key step at the basis of tumour initiation, driving the formation of a histologically differentiated pancreatic intraductal neoplasia (PanIN)." (PMID 35255936, 2022). "Preclinical reports have shown evidence linking oncogenic KRAS mutations and PD-L1 expression in cancers, which reduces the tumor-specific T cell’s function in the tumor microenvironment (TME)." (PMID 35785187, 2022). "The proposed strip test was applied, for the first time, for the simultaneous detection of the normal allele and three major single-point mutations of the KRAS gene in cell-free DNA and/or circulating tumor DNA from peripheral blood samples." (PMID 35200357, 2022). "Mutations in KRAS were clonal and concordant with extracranial disease, which suggests that these mutations are present within the primary tumour; however, further studies will be required to confirm this." (PMID 33024263, 2021). "In the current study, an NGS panel targeting exons 18, 19, 20, and 21 of EGFR, and exons 2 and 3 of KRAS was used to compare the mutation status of ctDNA and paired tumor tissue DNA (tDNA)." (PMID 33442424, 2021). "Using the large TCGA datasets, ALOX5 was reduced irrespective of tumour genotype with lowest expression observed in KRAS/LKB1 mutated tumours." (PMID 34203378, 2021). "KRAS mutations were found in 50% of the parental tumours (N = 8/16), BRAF V600E was present in 7% (N = 1/15) and MSI in 20% (N = 3/15)." (PMID 34572922, 2021). "All the patients underwent PET/CT scan before primary tumor resection, pathological samples were obtained, and the KRAS/NRAS/BRAF mutational status was evaluated." (PMID 34239564, 2021). "There is increasing evidence connecting KRAS mutations with tumor-promoting inflammation in several human cancers, including PDAC." (PMID 33802006, 2021).